IL18 (interleukin 18)
Diseases named in the same sentence as IL18 in open-access papers (continued):
Sharing a sentence is not in itself a finding about the gene and the disease.
tumor (continued). "Increased protein expression of caspase-1, IL1β, and IL18 occurred in surface epithelium, tumor cells, and immune cells." (PMID 31923221, 2020). "Inflammasome-IL-18 axis can act on natural killer (NK) cells to express fasL, thereby having a tumour-inhibiting effect." (PMID 32760201, 2020). "Cao and colleagues showed that leptin, by triggering M2 macrophage-related cytokine IL-18 production, contributes to tumour progression and the development of metastasis." (PMID 32033341, 2020). "We first assessed the immunofluorescence intensity of selected inflammasome components (NLRP1, NLRP3, NLRP6, AIM2, ASC, Caspase-1, IL-1β and IL-18) in tumor cells compared to normal epithelial cells, for each patient." (PMID 33255437, 2020). "The results from this comparative study demonstrate that the combined stimulation of γδ T cells via IL-2/IL-12/IL-18 is the most potent stimulus to enhance anti-tumor activity, proliferation and IFN-γ production in γδ T cells in the absence of TCR ligation." (PMID 31947966, 2020). "The anti-tumor effects mediated by local IL-12 secretion can also be enhanced by systemic administration of IL-18." (PMID 32708464, 2020). "Active IL-18 release facilitates expansion of intra-tumor effector T cells whereas intra-tumor macrophages are reduced." (PMID 33613285, 2020). "It was found that Interleukin (IL)-18 has a modifying role in the immune defense against tumor cells where it induces IFN-γ production." (PMID 31554361, 2019). "Conversely, IL-10 has been shown to limit inflammation, stimulate B cells, induce NK cell production of IFN-γ in concert with IL-18, and promote NK cell recognition of tumor cells, allegedly through the IL-10-mediated downregulation of tumor cell MHC." (PMID 31842362, 2019). "On the other hand, a tumor suppressing effect of IL-18 has been suggested due to its ability to activate immune cells, such as NK cells and T cells." (PMID 31731729, 2019). "IL-18 has been found to play a dual role in cancer, as it can promote tumor development, progression, migration, invasion, and metastasis." (PMID 31554361, 2019). "IL-18 also suppressed tumor growth and metastasis in implanted Lewis lung cancer, an effect it achieved by downregulating VEGF, thereby suppressing angiogenesis." (PMID 31293586, 2019). "IL-18, however, has also be shown to activate the anti-tumor immune response, resulting in the suppression of tumor growth and metastasis in multiple tumor types." (PMID 31231372, 2019). "Cytokine analysis in tumor patients revealed comparatively lower levels in IL-16, IL-18, CXCL8 (IL-8), IL-9, and CXCL10 (IP-10), indicating that the higher T cell numbers were not accompanied by increased T cell activity." (PMID 30740106, 2019). "The enhanced tumor burden was associated with reduced levels of both IL-1β and IL-18 which resulted in reduced STAT1 signaling and sub-optimal anti-tumor type I immunity." (PMID 31231388, 2019). "In contrast, up-regulation of Cd8b, Ifng and Il18 with combination treatment was highest at d28, coinciding with tumor regression." (PMID 31921384, 2019). "Tumor-derived IL-18 increases the immunosuppressive properties on NK subsets inducing their PD-1 expression which is correlated with poor prognosis of TNBC patients." (PMID 31430935, 2019). "Several studies have reported that tumor progression and IL-18 levels are positively correlated in various types of cancer." (PMID 31731729, 2019). "In several preclinical models, IL18 was found to have antitumor activity, however, its role is possibly tumor-specific." (PMID 31779626, 2019). "Contact with NB tumor cells or cytokine stimulation with IL-12+IL-18, mimicking activation by dendritic cells, led both to a CD107a expression in both NK cell subpopulations, and was even more pronounced within the CD16− NK cell population." (PMID 31849984, 2019). "Numerous animal tumor models have demonstrated broad anti-tumor activity for various cytokines, including GM-CSF, IL-2, IL-7, IL-12, IL-15, IL-18 and IL-21." (PMID 31856922, 2019).
tumor (continued). "Subsequently, IL-1β and IL-18 trigger the activation of the adaptive immune response to viruses and tumor cells." (PMID 31554368, 2019). "While IL-12 and IL-18 synergize Vγ2Vδ2 T cell-mediated cytotoxicity against tumor cells, IL-18 enhances the proliferative and recall response of Vγ2Vδ2 T cells from HIV-1-infected individuals." (PMID 31080452, 2019). "Alternatively, carcinoma-derived proteins were found to activate the NLRP3 inflammasome, which resulted in FasL-mediated NK cell cytotoxicity against metastatic tumor cells and effective tumor suppression after IL-18 activation of NK cells." (PMID 32010140, 2019). "IL-1β promotes angiogenesis by activating VEGF production during tumor progression, while IL-18 suppresses angiogenesis in cancer." (PMID 31580256, 2019). "Various types of cancer produce IL-18, and IL-18 induces cell migration, invasion, and proliferation, resulting in increased metastasis and tumor growth." (PMID 31731729, 2019). "In another study, it was shown that EVs derived from genetically modified cells expressing IL-15, IL-18, and 4-1BBL, similar to their host cells, were able to increase NK cell cytotoxicity in tumor cells following a short time treatment (4 h)." (PMID 30939820, 2019). "Multiple types of cell, including tumor cells and stromal cells, can produce and release IL-1β and IL-18 into the tumor microenvironment." (PMID 31492049, 2019). "Combination therapy with IL-18 and an immune-checkpoint inhibitor synergistically reduced mortality in mice harboring various tumor cell lines." (PMID 30717382, 2019). "Bacteria have also been used to deliver IL-18 into the tumor microenvironment to augment the T-cell mediated immune response." (PMID 31231372, 2019). "Given the studies demonstrating an anti-tumorigenic function for IL-18, numerous strategies are being investigated aimed at increasing the level of IL-18 in the tumor microenvironment and thus to augment the anti-tumor immune response." (PMID 31231372, 2019). "Some of the first evidence that IL-18 can promote tumor growth came from the observation of elevated expression of IL-18 by tumor cells or elevated levels of IL-18 in the serum of cancer patients, with elevated levels of IL-18 associated with poor prognosis." (PMID 31231372, 2019). "Pre-activation of NK cells with IL-2 or IL-12, IL-15 and IL-18 results in the generation of NK cells efficient to target and kill tumor cells." (PMID 30323819, 2018). "In one study, increased IL-18 levels were detected in serum and tumor tissues of patients with PC, and a higher tissue level of IL-18 correlated with increased metastasis and shorter survival." (PMID 29599908, 2018). "From single-cell RNA expression analyses of tumor-infiltrating lymphocytes, we found that the Interleukin-18 (IL-18) pathway is markedly upregulated in activated and dysfunctional CD8 T cells, suggesting its promise as an immunotherapeutic target." (PMID 30400822, 2018). "Caspase-1 can activate the pro-inflammatory cytokines IL-1β and IL-18, and promote inflammation and the formation of the tumor microenvironment, thus potentially promoting tumor infiltration and metastasis." (PMID 29626935, 2018). "We previously showed that the proinflammatory cytokine interleukin‐18 (IL‐18) has a tumor suppressive role in OSCC." (PMID 30524946, 2018). "NK cells can be primed by certain subsets of dendritic cells, by cytokines, such as IL-18, and by tumor cell lysates." (PMID 30286211, 2018). "Similar observations were confirmed in the current study as indicated by the association between decreased expression of IL-18 and protection against MDV as shown by the reduction of tumor incidence and MDV load in feathers." (PMID 30401976, 2018). "In the same study, the combination of the immunostimulatory cytokine IL-18 and liposomal doxorubicin significantly suppressed tumour progression in vivo, relative to the use of single agents." (PMID 30261606, 2018).
tumor (continued). "We report that expression of tankyrase 2 (TNKS2), β‐catenin, and N‐cadherin was higher in tumor cells than in normal mucosae, whereas the expression of IL‐18 and E‐cadherin was higher in normal than in tumor tissues." (PMID 30524946, 2018). "Using the TRUCK strategy to deliver IL-18 resulted in greater anti-tumor activity of CAR-T cells directed against the carcinoembryonic antigen in a pancreatic tumor model." (PMID 30420856, 2018). "Tumor-derived IL-18 was found to promote Kit+ NK cell transformation and mediate immunoablative functions in NK cell–controlled cancers." (PMID 29599908, 2018). "The increased tumor incidence found in Nlrp3−/− and Casp1−/− mice correlated with an important local reduction of Il-18 levels and an increased colonic infiltration of macrophages." (PMID 29868004, 2018). "Plasma interferon-γ and interleukin-18 concentrations in the xenograft tumor model after lipopolysaccharide (LPS) administration were significantly higher than those in the allograft tumor model." (PMID 29690614, 2018). "The secretion of ATP leads to the activation of P2RX7 receptor on DCs, resulting in the promotion of chemotaxis, tumour infiltration by inflammatory cells, and inflammasome-dependent release of the pro-inflammatory cytokines IL-1β and IL-18." (PMID 30261606, 2018). "Caspase-1 cleaves and activates the proinflammatory cytokines IL-1β and IL-18 into their mature peptides, which contribute to the down-stream inflammatory response and formation of tumor microenviroment." (PMID 28424426, 2017). "While the mechanism of action remains obscure, many studies have shown that tumor derived IL-18 not only provokes immuno-ablative NK cell expansion (i.e., immunosuppressive subsets) but also drives premature NK cell death." (PMID 28415798, 2017). "Upregulation of PD-1 expression was observed in CD56dimCD16dim/− NK cells, and this upshift was suppressed following RNAi-mediated knockdown of IL-18 in tumor cells." (PMID 28415798, 2017). "Adoptively transferred IL-12-, IL-15- or IL-18-activated murine NK cells are shown to display memory features and inhibit tumor growth in IFN-γ and perforin-dependent manner." (PMID 28955340, 2017). "Exposure to recombinant IL-18 or co-culture with IL-18-producing tumor cells, such as MDA-MB-231 or HeLa cells, increased the number of CD56dimCD16−/dim NK cells and concomitantly decreased the number of CD56dimCD16+ NK cells." (PMID 28415798, 2017). "Neutualization of these two inflammasomes released products, IL-1β and IL-18, has been suggested to be a promising therapeutic agent for tumor suppression in certain cancer types, indicating the importance of these two cytokines in the tumor microenvironment." (PMID 28591224, 2017). "We therefore investigated PD-1 expression in each NK cell subset and the change of PD-1 expression induced by exposure to tumor derived IL-18." (PMID 28415798, 2017). "It would be interesting to know the role of pyroptosis and gasdermin D, and their relationship with IL-1 and IL-18 in tumor development and therapies." (PMID 28955343, 2017). "Overall, our data demonstrate that treatment of DEX reduces expression of pro-inflammatory cytokines, especially IL-1β and IL-18, and thus enhances immunosurveillance in the tumor microenvironment and anti-metastatic actions." (PMID 28591224, 2017). "To verify the contribution of tumor derived IL-18 to the differentiation of NK cells, we depleted IL-18 using siRNA." (PMID 28415798, 2017). "IL-18, belonging to IL-1 super family, is a pleiotropic proinflammatory cytokine with dual effects on tumor development and progression." (PMID 29312552, 2017). "Active IL-1β and IL-18 can regulate the differentiation of tumor and T helper (Th) cells through downstream signal molecules including NFκB and IL-6." (PMID 29312552, 2017).
tumor (continued). "In this experiment, the cytokine response analyses showed significant up-regulation of IL-12, IL-2, IL-15 and IL-18 in the progressors, which reflects an anti-tumor immunity in the rapidly growing tumors." (PMID 28381295, 2017). "Human IL-12-, IL-15-, and IL-18-induced memory-like NK cells show higher expression of granzyme B and perforin and display enhanced cytotoxicity against K562 tumor cells." (PMID 28955340, 2017). "It has been reported that the levels of TAM-derived tumor growth factor-β1 (TGF-β1), epidermal growth factor (EGF), chemokine [C-C motif] ligand 18 (CCL18), interleukin (IL)-18, IL-1β, and IL-8 are correlated with tumor progression." (PMID 28143526, 2017). "Next, we investigated the clinical implications of tumor derived IL-18 in EBC patients with respect to relapse and survival." (PMID 28415798, 2017). "Based on these data, tumor-derived IL-18 plays an immunosuppressive role via its regulation of NK cell subsets." (PMID 28415798, 2017). "The inhibition of inflammasomes or neutralization of their products, mainly IL-1β and IL-18, has profound inhibiting effects on carcinogenesis and tumor progression." (PMID 29312552, 2017). "One of the putative metastasis-promoting roles of tumor derived IL-18 is to induce the expression of PD-1 on mature NK cells." (PMID 28415798, 2017). "In conclusion, we show that tumor-derived IL-18 induced PD-1 expression on immunosuppressive CD56dimCD16dim/− NK cells and is associated with poor prognosis in TNBC." (PMID 28415798, 2017). "Higher expression or secretion of IL-18, however, has been detected in various cancer cells, and tumor derived IL-18 has been shown to be a poor prognostic factor in cancer." (PMID 28415798, 2017). "In line with this notion, IL-18 is considered to be a promising anti-tumor immunotherapy, either as a monotherapy or in combination with a monoclonal antibody." (PMID 28415798, 2017). "Tumor-derived IL-18 increased the immunosuppressive CD56dimCD16dim/− NK cell fraction and induced PD-1 expression on these NK cells." (PMID 28415798, 2017). "Overall, our data suggest that DEX, even at such a low dose, suppressed the expression of proinflammatory cytokines, namely IL-1β and IL-18, and the concordant decrease in MDSCs and TAMs in the tumor stroma." (PMID 28591224, 2017). "We found that tumor implantation increased interleukin (IL) 6 expression in iWAT, while alcohol consumption increased IL18 expression in tumor-bearing mice." (PMID 29245988, 2017). "Not only does IL-1B appear positively correlated with MAP17 in all tumors, other interleukins including IL-15, IL-18, IL-1A, IL-32 and IL-7 and interleukin receptors including IL-10RB, IL-17RC and IL-2RG appear in at least three of the tumor types." (PMID 29228712, 2017). "Serum IL-18 levels were significantly higher in BCa patients when compared to the control subjects, however, the relationship between IL-18 and tumor progression need to be further determined." (PMID 29190997, 2017). "Thirdly, neutrophils have been proved to contain and secrete vascular endothelial growth factor, IL-18, and matrix metalloproteinases, which directly contribute to tumor-related angiogenesis, tumor growth, and metastasis." (PMID 27087737, 2016). "Gene therapy studies that increase of IL-18 has been shown to provide test animals with protection against infection, tumour growth, and metastases." (PMID 28100936, 2016). "After in vitro verification of secretion of active IL-18, mice with subcutaneous K-BALB and CT26 tumors were injected with SFV-IL-18 particles, which led to tumor regression and disappearance of tumors in some treated animals." (PMID 27827980, 2016). "Of note, proinflammatory cytokines such as TNFα and IL-6 were elevated in the tumor microenvironment, whereas the level of IL-18 was significantly reduced." (PMID 27206676, 2016). "CART cells exposed to IL-2 or IL-15 lysed SKOV3 cells more efficiently than those exposed to IL-18 or NC, even at the lowest T cell to tumor ratio." (PMID 27409425, 2016).
tumor (continued). "In the present study, a systematic comparative analysis of the effects of different γc cytokines and IL-18 on the ex vivo expansion, phenotype, and anti-tumor activity of CART cells in vitro and in vivo was conducted." (PMID 27409425, 2016). "In contrast, other studies reported enhanced expression of IL-18 induced by Lf in the small intestine of tumor-bearing mice." (PMID 26990190, 2016). "In other words, (ruxolitinib + ERBB1/2/4 inhibitor) treatment initially reduces CXCL-1, IL-8, and IL-18 expression that then rebounds in the surviving tumor cells, being over-expressed cf in vitro multiplex data in." (PMID 27379204, 2016). "While TLR8-inducible mediators, including IL-12 and IL-18, act cooperatively on NK cells, additional signals including tumor-expressed NKG2D ligands, and FcγRIII activation via ADCC, intensify the response." (PMID 26928328, 2016). "Vascular endothelial growth factor, interleukin-18, and matrix metalloproteinases, secreted by circulating neutrophils, contribute to the tumor-related angiogenesis, tumor growth, and metastasis." (PMID 27087737, 2016). "CT26/GM-CSF, CT26/IL18, and CT26/GM-CSF/IL-18 cells (1 ×106 of each) were inoculated subcutaneously into Balb/C mice, and tumor volume was monitored from tumor-bearing mice every 3 or 4 days." (PMID 26186692, 2015). "Although hUMSCs/IL-18 significantly suppressed the growth and invasion of cancer cells, IL-18 has also been found to promote tumor progression." (PMID 25780408, 2015). "Evidence has indicated that IL-18 exerts anticancer effects by inhibiting tumor angiogenesis and growth." (PMID 25591548, 2015). "IL-18 can stimulate natural killer cells and T cells promoting primarily Th1 responses, resulting in the elimination of tumor cells." (PMID 26376814, 2015). "On the other hand, it has been reported that IL-18 is able to induce angiogenesis, migration, proliferation, and immune escape of tumor cells." (PMID 26376814, 2015). "A low secretion of IL-18 can lead to the failure of natural killer cell activation and of tumor eradication in old mice." (PMID 26447695, 2015). "Co-expression of IL-18 significantly reduced tumor growth (P<0.05) and improved the tumor protective effects (P<0.05) when compared with GM-CSF alone." (PMID 26186692, 2015). "Experimental studies in mice have proven synergistic effects of IL12 and IL18, suppressing collateral or distant tumor growth." (PMID 25967290, 2015). "Co-expression of GM-CSF and IL-18 reduced tumorigenesis (P<0.05) and enhanced tumor protective efficacy (P<0.05) significantly in comparison with GM-CSF alone." (PMID 26186692, 2015). "Co-expression of membrane-bound IL-18 and GM-CSF significantly enhanced the tumor inhibitory effects of GM-CSF (P<0.05)." (PMID 26186692, 2015). "The data showed that compared with cells transfected with the control vector, IL-18 expression activated caspase-3 and -7 and subsequently induced tumor cell apoptosis, as analyzed by flow cytometry." (PMID 25591548, 2015). "The antitumor activities of hUMSCs/IL-18, i.e. the inhibition of tumor cell growth, as well as migration and invasion, were confirmed by coculture in Transwell chambers in the present study." (PMID 25780408, 2015). "The results indicated that the hUMSC/IL-18-dependent tumor cell growth attenuation occurred predominantly due to cell cycle arrest at the G1/S check point." (PMID 25780408, 2015). "Recently, the enhanced anti-tumor effect was also reported on Lewis lung cancer cells LL/2 modified to co-express soluble GM-CSF and IL-18 as a tumor vaccine." (PMID 26186692, 2015). "Cancer vaccines employing unmodified exosomes or exosomes engineering to express particular molecules derived from tumor cells such as IL-18 or HSP induced specific anti-tumor immunity." (PMID 25999947, 2015). "Interleukin (IL)-12 and IL-18 have been employed as they synergistically stimulate cytotoxic T-cells and natural killer cells, which are typically involved in anti-tumour immune responses." (PMID 26100265, 2015).